CFAP68 (cilia and flagella associated protein 68)
Description:
Microtubule inner protein (MIP) part of the dynein-decorated doublet microtubules (DMTs) in cilia axoneme, which is required for motile cilia beating.
Synonyms: C11orf1; FLJ23499
Tractability: Small molecule: a structure with a bound ligand is known.
Gene: Protein-coding gene on chromosome 11 (111,878,935 to 111,885,975, forward strand). Ensembl gene ENSG00000137720.
Subcellular location: Cytoplasm, cytoskeleton, cilium axoneme; Cytoplasm, cytoskeleton, flagellum axoneme; Nucleus; Cell projection, cilium
Subcellular location (Human Protein Atlas): Nucleoplasm
Gene Ontology:
Molecular function: protein binding
Biological process: flagellated sperm motility
Cellular component: axoneme; cilium; nucleoplasm; nucleus; axonemal A tubule inner sheath; sperm flagellum
Genetic constraint (gnomAD): Loss-of-function variants: 26 observed, 20.88 expected, observed/expected ratio (o/e) 1.25, 90% interval 0.91 to 1.71. The upper end of that interval is the gene's LOEUF score, 1.71, which puts it in group 6 of 6, group 1 being the genes least tolerant of losing a copy. Missense variants: 174 observed, 172.48 expected, observed/expected ratio (o/e) 1.01, 90% interval 0.89 to 1.14. Synonymous variants: 60 observed, 60.99 expected, observed/expected ratio (o/e) 0.98, 90% interval 0.8 to 1.22.
Homologues: Orthologues: macaque CFAP68 (96% identical), chimpanzee CFAP68 (91% identical), rabbit CFAP68 (83% identical), dog C5H11orf1 (82% identical), rat Cfap68 (78% identical), mouse Cfap68 (75% identical), zebrafish cfap68 (44% identical), tropical clawed frog CFAP68 (38% identical).
Diseases named in the same sentence as CFAP68 in open-access papers:
CFAP68 is named in the same sentence as 2 diseases in open-access papers, as found by Europe PMC text mining. Sharing a sentence is not in itself a finding about the gene and the disease.
CFAP68 shares sentences with these, for which no sentence is quoted: breast carcinoma (1 paper); rubella (1).